NTN1 (netrin 1)
Diseases named in the same sentence as NTN1 in open-access papers (continued):
Sharing a sentence is not in itself a finding about the gene and the disease.
tumor (continued). "The study also observed an increase in the methylation levels of genes (NTN1, MYH10) involved in tumor development, progression, proliferation, and migration." (PMID 38201971, 2023). "Briefly, knock-down of MEF2C-AS1 promoted aggressive tumor behaviors by reducing the protein levels of FAT3, NTN1, and LYVE1 which were related to proliferation and invasion in GC cell lines." (PMID 36064442, 2022). "The netrin-1-FAK axis was considered as an inducer of the migration and adhesion of many tumor cells." (PMID 35974411, 2022). "Taken together, our data support the view that NTN1 and its NEO1 receptor are upregulated in the NB tumor niche, triggering metastasis." (PMID 33724150, 2021). "In these tumors, the gain of netrin-1 or the deletion of Unc5b and DCC prevents tumor cells from undergoing apoptosis and thereby promotes tumor growth and metastases." (PMID 35008701, 2021). "Netrin-1 and its receptors, DCC and UNC5H, have been reported to be important factors for tumor development and progression in several tumor entities." (PMID 29854303, 2018). "Using this strategy NTN1 and CXCL4V1 have been identified as key tumor-promoting factors produced in pancreatic tumor cells." (PMID 29662633, 2018). "Thus, we hypothesized that UNC5A may be a key receptor involved in netrin-1-mediated tumor growth." (PMID 28710382, 2017). "Using a netrin-1 interfering antibody, they demonstrate both in vitro and in vivo that netrin-1 acts as a survival factor for ABC-DLBCL and MCL tumor cells." (PMID 27398102, 2016). "The integrin β4-knockdown cells exhibited a significantly reduced tumor-forming ability, indicating that integrin β4 is actively involved in regulating PDAC progression and at least partially mediates the netrin-1-induced suppression of PDAC." (PMID 27034160, 2016). "The protein expression of netrin-1 and UNC5B showed the same trend as that of mRNA expression, and the optical density of all tumor (T) & normal (N) tissues were measured and expressed graphically." (PMID 24528886, 2014). "Our findings that FGFR signaling induces lymphangiogenic molecules in lymphatic endothelial cells, including VEGFR-2, VEGFR-3, netrin-1 and integrin α9, also validate the idea of FGF acting in a paracrine manner on tumor lymphatic endothelial cells." (PMID 22761819, 2012). "Because netrin-1 and its receptors have already been reviewed for their role in neuronal guidance, we will mainly describe here the implications of netrin-1, DCC and UNC5H in apoptosis and consider the consequences on tumour escape mechanisms." (PMID 15956977, 2005). "Co-immunofluorescence showed that NTN1 and NEO1 were co-expressed in tumor cells in KPC mice." (PMID 40777309, 2025). "overexpressed NTN1 and found that MDM2 expression levels increased, Cyclin D1 expression declined, which then induced enhanced cellular invasiveness in vivo and in vitro, and provided adhesion substrates for tumour cells." (PMID 38546656, 2024). "reduced the expression of NTN1 in NB cells and found that the UNC5H/DAPK signal pathway was triggered, resulting in an increase in cell death while inhibiting the dissemination and transfer of tumour cells in the nude mice." (PMID 38546656, 2024). "Moreover, NTN1 overexpression significantly inhibited the expression of SOX6, reversing the effects of SOX6 on cell proliferation and invasion in vitro and tumour xenograft growth and vascularity in vivo." (PMID 38546656, 2024). "Collectively, these findings suggest that the upregulated NTN1 gene expression in VAT from patients with OB and CC promotes a pro-inflammatory microenvironment that may trigger tumour progression and migration." (PMID 36831381, 2023). "Netrin-1 interacts with neo-genin (neonatal protein), enhances the chemotaxis of CD4 + T cells, and triggers a pro-inflammatory response, playing a key role in the regulation of the tumor microenvironment." (PMID 37568074, 2023).
tumor (continued). "Netrins have, however, been found to play a role in tumor biology, where in particular DCC and UNC5 positively regulate apoptosis in the absence of netrin-1 but negatively regulate apoptosis in the presence of netrin-1." (PMID 36499024, 2022). "The expression level of netrin-1 in peripheral blood samples of children with B-ALL and children without neoplasia was measured by enzyme-linked immunosorbent assay (ELISA) kits." (PMID 35974411, 2022). "Different cell types in the tumor microenvironment in GBM such as glial cells (astrocytes and oligodendrocytes), microglia, infiltrating immune cells (monocytes, macrophages, and lymphocytes), EC, and pericytes can express Netrin-1 and its receptors." (PMID 34361013, 2021). "In addition to the participation of canonical angiogenic molecules, overexpression of Netrin-1, originally discovered as a neural guidance cue, has recently been described in GBM and an important role of this ligand in tumor angiogenesis has been proposed." (PMID 34361013, 2021). "As we have highlighted, tumor angiogenesis in GBM is also promoted by the expression of non-canonical angiogenic molecules such as Netrin-1." (PMID 34361013, 2021). "Moreover, Netrin-1 expression is higher in type III and IV tumors, being related to cell aggressiveness and tumor progression." (PMID 34361013, 2021). "Thus, our results presented herein, which reveal a previously unrecognized function of netrin-1 as a suppressor of BMP signaling, are consistent with a tumor-promoting function of netrin-1 that is achieved via the suppression of BMP signaling." (PMID 33883596, 2021). "Although the role that Netrin-1 plays in GBM has been described, it is necessary to study the way it is secreted by tumor cells and the possible signaling pathways through which it could promote neovascularization in GBM." (PMID 34361013, 2021). "Although the presence of Netrin-1 in microvesicles derived from GBM tumor cells has not been reported to date, other molecules with similar functions have been found in exosomes." (PMID 34361013, 2021). "The high expression of NTN1, NTN3, and NTNG1 is also sensitive to MS-275 (HDAC inhibitor), RG-108 (DNA methyltransferase inhibitor), and CUDC-101 (HDAC inhibitor, EGFR inhibitor, and HER2 inhibitor), which inhibit tumor by affecting epigenesis." (PMID 32251318, 2020). "Methylation of ETNK2, NTN1, and NUDT10 was increased in ERG-fusion negative tumors, which is concordant with the significant loss of TET2 expression in these tumor samples." (PMID 30917865, 2019). "However, netrin-1 shortage induces cleavage of DCC at its intracellular domain and promotes apoptosis; thus, DCC is considered as a tumor suppressor." (PMID 30373548, 2018). "SEMA3F and netrin-1 have multifaceted effects on tumor and surrounding non-tumor cells, including ECs, leukocytes, macrophages, and fibroblasts." (PMID 30532711, 2018). "Kaplan-Meier plots and log-rank tests showed that patients with high netrin-1 expression and low UNC5B expression in their tumor tissues had statistically significant shorter survival rate compared with those with low netrin-1 expression and high UNC5B expression (P < 0.01)." (PMID 24528886, 2014). "Together, these data support the view that Doxorubicin triggers netrin-1 upregulation specifically in tumours and not in normal tissues; an effect that can be used to potentiate the anti-tumour effect of netrin-1 interfering agents." (PMID 24293316, 2013). "Sequencing of the patient-1 tumor sample yielded 497 total cells, with 92 cells (19%) identified as HGSOC cells, from which we identified only four somatic fusion transcripts: SMG7::CH507-513H4.1 (26 cells), RAPGEF5::AGMO (6 cells), NTN1::CDRT15P2 (five cells), and GS1-279B7.2::GNG4 (five cells)." (PMID 40086881, 2025).
tumor (continued). "Sequencing of the Patient-1 tumor sample yielded 497 total cells, with 92 cells (19%) identified as HGSOC cells, from which we identified only four somatic fusion transcripts: SMG7::CH507–513H4.1 (26 cells), RAPGEF5—AGMO (6 cells), NTN1--CDRT15P2 (5 cells), and GS1–279B7.2--GNG4 (5 cells)." (PMID 38464114, 2024). "In addition to the role in axon guidance and neurite outgrowth, DCC is proapoptotic and prevents tumour growth when it is not activated by Netrin-1." (PMID 35562959, 2022). "Moreover, Netrin-1 promotes the expression of C-MYC, which could favor neovascularization in the tumor niche." (PMID 34361013, 2021). "Moreover, how tumor cells process, pack, and secrete Netrin-1 towards the tumor microenvironment has not been described either." (PMID 34361013, 2021). "Netrin-1 also has a number of non-neuronal functions: regulating angiogenesis, inflammation, and tumor progression." (PMID 30532711, 2018). "This antibody could block Netrin-1/Unc5B interaction to inhibit Netrin-1 induced tumor cell growth but does not inhibit Netrin-1/DCC interaction, suggesting that DCC and Unc5B also could interact with different Netrin-1 motifs in the EGF2 domain." (PMID 28245592, 2017). "In contrast, NTN1 and Notch2 did not co-localize in same tumor cells." (PMID 28069038, 2017). "Similarly, other studies suggest that neogenin could induce chemoattraction or chemorepulsion after binding to ligands such as netrin-1 and RGM to influence tumor cell migration and invasion." (PMID 25416629, 2014). "Additionally, we analyzed patients with absence of nuclear netrin-1 expression and compared them to the patient group showing highest nuclear netrin-1 expression (>40% of tumor cells)." (PMID 24647424, 2014). "Moreover, in a model of xenografted nude mice, we show that systemic Doxorubicin treatment triggers netrin-1 upregulation in the tumour but not in normal organs, enhancing and prolonging tumour growth inhibiting effect of a netrin-1 interfering drug." (PMID 24293316, 2013). "Two drug candidates, TRAP-netrinDCC and TRAP-netrinUNC5A, which are Fc-fused and stabilized ectodomains of respectively DCC or UNC5A, have been shown to trigger death of netrin-1 expressing tumour cells in vitro and tumour growth inhibition in engrafted mice models (not shown)." (PMID 24293316, 2013). "Drawing from CAF strategies, inhibiting netrin-1, a CAF-derived factor that promotes cancer cell stemness, could target CAA-derived factors that sustain dedifferentiated, tumor-supportive states, thereby reducing their plasticity-driven effects on tumor progression." (PMID 40784879, 2025). "Moreover, our recent studies demonstrate that netrin-1/neogenin interactions augment CD4+ T cell chemokinesis and elicit pro-inflammatory responses, suggesting that netrin-1 plays a key role in modulating the function of a tumor and its surrounding cells in the tumor microenvironment." (PMID 30532711, 2018).
psychiatric disorder (9 papers, 2020 to 2024). A disorder characterized by behavioral and/or psychological abnormalities, often accompanied by physical symptoms. "Netrin-1 is critical to dopaminergic neurons in substantia nigra of the brain and its deficiency is critical in both PD pathogenesis and development of psychiatric disorders." (PMID 38638604, 2024). "This association of Netrin-1/DCC with certain psychiatric disorders can be related to the expression of these factors in the ventral tegmental area, nucleus accumbens and orbitofrontal cortex, all part of the limbic system." (PMID 33195252, 2020). "Factors regulating either DCC or Netrin-1 in adolescence can disrupt mesocorticolimbic dopamine development, rendering vulnerability or protection to phenotypes associated with psychiatric disorders." (PMID 32714924, 2020). "The NTN1/DCC signaling pathway, interacting with UNC5C, plays a crucial role in central nervous system axon guidance and has been associated with psychiatric disorders during adolescence in humans." (PMID 38540364, 2024). "The psychiatric disorders are related to the mesocorticolimbic dopamine system which involves the Netrin-1/DCC signaling pathway." (PMID 38638604, 2024). "This striking finding indicates that the effects of DCC and Netrin-1 are important across a wide variety of psychiatric disorders." (PMID 31659271, 2020). "An important question is whether social stress in adolescence interferes with the Netrin-1/DCC pathway, disrupting the proper development of mPFC DA connectivity and ultimately causing cognitive impairments shared across multiple psychiatric disorders." (PMID 33619036, 2021). "Since impairments in PFC function are characteristic of multiple psychiatric disorders, the Netrin-1/DCC pathway may represent a critical target for early intervention and treatment strategies." (PMID 33619036, 2021). "Our findings provide important mechanistic insight regarding the critical role for the Netrin-1/DCC system in adolescent neurodevelopment, and its strong link to psychiatric disorders of an adolescent onset." (PMID 37419977, 2023). "This review highlights accumulating evidence that Netrin-1 and its receptor DCC contribute to mesocorticolimbic dopamine related psychiatric disorders that emerge during adolescence." (PMID 31659271, 2020).
infection (8 papers, 2015 to 2025). The state of being infected such as from the introduction of a foreign agent such as serum, vaccine, antigenic substance or organism. "In a novel and indirect approach to study Netrin-1 protein production, we investigated the association of Netrin-1 mRNA with endoplasmic reticulum (ER) membrane-bound polysomes, in which the translation of this secreted protein takes place, or with free polysomes, upon infection." (PMID 27031829, 2016). "In this regard, an in vitro and in vivo study by Ly et al11 revealed that infection and pro-inflammatory models significantly decreased the level of macrophage-derived netrin-1, promoting the attraction of leukocytes to the site of inflammation." (PMID 35919444, 2022). "Infection with the Netrin-1 shRNA constructs differentially downregulated Netrin-1 expression in comparison to the Netrin-1-Flag construct and the scrambled sequences." (PMID 32714924, 2020). "Over the five- to ten-day kinetic follow-up study, HCV induced an 8-fold increase in the levels of Netrin-1 mRNA at day eight post-infection in proliferating cultures infected with an HCV JFH1 isolate or with a genotype 1 strain and in differentiated cells." (PMID 27031829, 2016). "Additionally, Passacquale et al24 reported that netrin-1 is downregulated by infection and pro-inflammatory cytokines, leading to a decrease in netrin-1 protective effects on endothelial cells, which accelerates inflammation progression." (PMID 35919444, 2022). "In addition to its roles in chronic inflammation, we and others have shown that netrin-1 expression by endothelial or epithelial cells can protect from inflammation due to infection and ischemia." (PMID 31428465, 2019). "Since LARP1 intriguingly concentrates at the ER and in the proximity of lipid droplets, an important viral budding site, upon infection, we tested whether accumulation of Netrin-1 in microsomes could foster increased morphogenesis, through the evaluation of the specific infectivity of virions." (PMID 27031829, 2016). "Netrin-1 mRNA expression was significantly repressed by shNetrin-1, and HBV-DNA levels, as determined by quantitative PCR (qPCR), were substantially increased after infection for 10 days." (PMID 41406170, 2025).
kidney (7 papers, 2011 to 2024). "Furthermore, deletion of Ntn1 resulted in a delay in the cessation of nephrogenesis and kidney hypoplasia." (PMID 37131589, 2023). "Hence, our observation that EGFR undergoes functional upregulation by Netrin-1 indicates that it may mediate the potentially deleterious effects of Netrin-1 in liver pathologies." (PMID 27031829, 2016).
cardiovascular disease (5 papers, 2016 to 2020). "Layne K, Ferro A, Passacquale G. Netrin-1 as a novel therapeutic target in cardiovascular disease: to activate or inhibit?" (PMID 32267322, 2020). "Netrin-1 as a novel therapeutic target in cardiovascular disease: to activate or inhibit?" (PMID 32267322, 2020). "In the context of cardiovascular disease, netrin-1 is already being considered as a therapeutic agent with human netrin-1 gene delivery resulting in significantly reduced atherosclerotic plaque formation in low-density lipoprotein receptor knockout mice being fed a high cholesterol diet." (PMID 27509208, 2016). "Currently, the therapeutic potential of netrin-1 has largely centred on cardiovascular disease with debate surrounding whether netrin-1 contributes to, or reduces atherosclerotic plaque formation." (PMID 27509208, 2016). "Given the emerging role of netrin-1 in cardiovascular disease and as an oncological target, further delineation of the pathways that control netrin-1 production under both physiological and pathological conditions, may allow development of useful and novel therapies based on netrin-1 modulation." (PMID 29156815, 2017).
neurological disorders (5 papers, 2015 to 2025). "Here we provide an overview of Netrin-1 to highlight its mechanistic roles and biomarker potentials in these neurological disorders." (PMID 38638604, 2024). "List of neurological disorders and other clinical diseases that involves Netrin-1." (PMID 38638604, 2024). "The role of Netrin-1 in neurological diseases has been widely reported." (PMID 35493300, 2022).
kidney disease (4 papers, 2014 to 2021). "Animal studies show that netrin-1 plays a protective role in epithelial cells whereas sema3A may have a pathogenic role in kidney disease." (PMID 25289643, 2014). "Development of netrin-1 based therapies or small molecule that can activate its receptor UNC5B will be able to treat not only kidney disease but also the inflammatory disease of other organs as well." (PMID 24991088, 2014).
neurodegenerative disease (4 papers, 2020 to 2025). A disorder of the central nervous system characterized by gradual and progressive loss of neural tissue and neurologic function. "Recent studies highlight the dual roles of Netrin-1 in neuroinflammation and neurodegenerative diseases." (PMID 40761377, 2025). "Netrin-1, a central axonal guidance molecule discovered for its role in neuronal development, is also essential in neurodegenerative diseases." (PMID 40761377, 2025). "In addition to developmental functions, the role of Netrin-1 in neuroinflammation and neurodegenerative diseases emphasizes its crucial role in regulating cell–cell interactions and maintaining neurological integrity." (PMID 40761377, 2025). "Moreover, researchers should pursue to find specific molecular targets of Netrin-1 for neurodegenerative disease." (PMID 40761377, 2025). "Different studies assess the role of Netrin-1 in neuroinflammation and neurodegenerative diseases." (PMID 40761377, 2025). "In this review article, we aimed to introduce some fruitful data about Netrin-1's impact on neurodegenerative diseases so that its positive and negative aspects can be used in future research." (PMID 40761377, 2025). "A recent study reveals a significant decrease in plasma Netrin-1 levels with a positive correlation with UPDRS (Unified Parkinson’s Disease Rating Scale) scores in PD patients, strongly supporting its biomarker potential in this second most common neurodegenerative disease." (PMID 38638604, 2024).
inflammation (3 papers, 2010 to 2025). Aberrant reaction of the microcirculation characterized by movement of fluid and leukocytes from the blood into extravascular tissues. "Together, these studies suggest a dual role for Netrin-1 as both an initiator and amplifier of chronic adipose inflammation." (PMID 40949120, 2025). "Utilizing mice with partial netrin-1 deficiency (Ntn-1+/− mice) we found that these mice are more prone to AKI-induced kidney dysfunction and renal inflammation." (PMID 21625583, 2011). "As such, netrin-1 dampened a crucial component of lung injury, since pulmonary inflammation is the major contributor to the pathological derangement of ALI." (PMID 20969752, 2010).